VIM (vimentin)
Diseases named in the same sentence as VIM in open-access papers (continued):
Sharing a sentence is not in itself a finding about the gene and the disease.
colitis (16 papers, 2012 to 2025). Inflammation of the colon. "E-cadherin levels appeared to increase in the CR group but decreased as inflammation proceeded, while Vimentin levels intensified with more severe colitis." (PMID 40839695, 2025). "Co-localization of DCLK1 staining with Vimentin revealed a rapid increase in Vimentin expression levels as inflammation progressed and was sustained with more severe colitis, which is in clear contrast to the E-cadherin/DCLK1 patterns previously observed." (PMID 40839695, 2025). "Of note, there is a study revealed that SBS markedly alleviated colitis-associated CRC through inhibition of EMT induced by TGF-β1 signaling, shown as down-regulating Snail, N-cadherin, fibronectin, and vimentin, whereas up-regulating E-cadherin expression." (PMID 35308223, 2022). "CSA13 treatment significantly inhibited colonic collagen Col1a2 mRNA expression and fibroblast accumulation (αSMA and vimentin) in the mice with TNBS colitis that was reversed by Fpr2 shRNA." (PMID 29180648, 2017). "Recent studies showed that mice with vimentin are more susceptible to colitis compared to mice lacking vimentin, likely due to its interactions between vimentin and the p47phox active subunit of NADPH oxidase." (PMID 39139560, 2024). "Furthermore, Vim−/− mice have increased tumor size and number in the distal colon comparing with WT mice, which indicates that vimentin has a crucial role in colitis induction and tumorigenesis of the colon." (PMID 35399505, 2022). "To test whether the deletion of vimentin is prone to chronic injury-associated cancer, we introduced a AOM plus DSS colitis-associated colorectal model to resemble the pathology of human colitis-associated neoplasia." (PMID 35399505, 2022). "Vimentin was recently shown to be involved in the experimental murine colitis." (PMID 35399505, 2022). "Thus, vimentin has a crucial role in protection from colitis induction and tumorigenesis of the colon." (PMID 35399505, 2022). "IL-11+ cells associated with colitis were also positive for vimentin, collagen I, and collagen IV, but not αSMA, suggesting that these cells were fibroblasts, but not myofibroblasts." (PMID 33863879, 2021). "In addition, AOAA also restored the expression of vimentin in mouse colonic tissue with DSS-induced colitis." (PMID 35299827, 2021). "Our results show that inhibition of PFKFB3 indeed hampers the inflammation in DSS-induced colitis, simultaneously also decreasing the number of activated/fibrotic stromal cells (highlighted by reduced levels of collagen, α-SMA, and vimentin)." (PMID 36405760, 2022). "Over 90 percent of Citrine+ cells in DSS-induced colitis and IL10−/− colitis were vimentin+ fibroblasts." (PMID 33953267, 2021). "Using IL-33-citrine reporter mice (Il33Cit/+), we show that vimentin+CD90+ fibroblasts are the source of IL-33 at baseline and this population increases in DSS-induced colitis." (PMID 33953267, 2021). "We showed here that the loss of vimentin in vivo leads to susceptibility to develop colitis-associated CRC upon the combination of AOM carcinogen treatment and DSS inflammatory injury, whereas the deletion of vimentin alone does not predispose to colitis-associated CRC." (PMID 35399505, 2022).
prostate tumor (16 papers, 2010 to 2025). "Overexpression of TGF-β leads to upregulation of vimentin and NF-κβ in prostate tumors with high and intermediate Gleason grades." (PMID 31842336, 2019). "Accordingly, our previous work had already demonstrated an increased expression of vimentin when stromal cells were exposed to prostate tumor cell lines, besides changes in its cellular arrangement from punctate to a fibrilar distribution." (PMID 25887999, 2015). "Of note, we discovered a positive correlation between UBE2T and vimentin expression, both expression levels of UBE2T and vimentin are associated with the malignant properties of prostate tumors." (PMID 26308072, 2015). "We then investigated a possible link between CR-1 and EMT in human primary prostate tumors by examining expression of vimentin, a robust marker of mesenchymally-derived cells or cells undergoing an EMT." (PMID 25596738, 2015). "Additionally, overexpression of vimentin induced by stable transfection of expression constructs in tumoral cells was unable to enhance invasiveness in poorly invasive prostatic tumor or was shown, on the contrary, to decrease hepatocarcinoma proliferation." (PMID 20169076, 2010). "Therefore, down-regulation of vimentin could prevent the translocation of ERK which means decreased prostate tumour growth, adhesion, and invasion as well as apoptosis induction." (PMID 23690850, 2013). "The expression of miR-539 in prostate tumors is decreased, contributing to elevated expression of DLX1, which in turn facilitates TGF-β-induced changes in expression of e-cadherin, vimentin, Snail1, and Slug, synonymous with epithelial–mesenchymal transition." (PMID 31842336, 2019). "Oral administration of WA inhibited the expression of β-catenin, vimentin, and snail/slug (data not shown) and induced E-cadherin in prostate tumor samples, suggesting prevention of metastasis." (PMID 27447565, 2016).
rhabdomyosarcoma (16 papers, 2005 to 2025). A rare aggressive malignant mesenchymal neoplasm arising from skeletal muscle. "In immunohistochemical staining, rhabdomyosarcoma (RMS) exhibits positive expression of vimentin, desmin, myogenin, and MyoD1." (PMID 40703554, 2025). "The neoplastic cells of rhabdomyosarcoma were positive for vimentin, desmin, myoglobin and muscle-specific actin." (PMID 36641746, 2023). "Rhabdomyosarcomas expressed vimentin, desmin, myoD1, and myogenin." (PMID 35001360, 2022). "Immunohistochemical studies of deparaffinized tissue may show rhabdomyosarcoma cells to be positive for vimentin, which indicates a mesenchymal phenotype." (PMID 35228875, 2022). "The most useful immunohistochemical marker includes antibodies against muscle-specific actin and desmin, which show the greatest specifity, vimentin shows a positive reaction in most rhabdomyosarcoma but is less specific for this tumor because it can be positive in other malignancy." (PMID 24716058, 2014). "Notably, the components of rhabdomyosarcoma exhibited a strong positive reaction for desmin and a moderate positive response for myoglobin, the undifferentiated spindle cell component demonstrated a positive immunoreactivity solely for vimentin." (PMID 40832615, 2025). "On IHC staining, the neoplastic cells in pleomorphic rhabdomyosarcoma show positive reactivity with myogenin, desmin, smooth muscle actin (SMA) and vimentin." (PMID 34034720, 2021). "EV-A71-289A and EV-A71-289T were used to infect human rhabdomyosarcoma cells, control human brain microvascular endothelial cells (HBMECs), and VIM-knockout (KO) HBMECs and inoculated BALB/c mice, SV129 mice, and VIM-KO SV129 mice." (PMID 31121933, 2019). "Mixed germ cell tumor, most often metastasis from testicular primary, with somatic teratomatous malignancy (rhabdomyosarcoma) can be excluded by positive staining of PLAP and cytokeratins and negative staining of vimentin, Melan-A and calretinin." (PMID 20687934, 2010).
asthma (15 papers, 2013 to 2026). "Elevated ITGA5 expression correlated positively with reduced lung function, asthma severity and higher levels of EMT regulators (Fibronectin, N-cadherin, Vimentin) and was functionally linked to anoikis resistance." (PMID 41772919, 2026). "Multivariate analysis revealed that elevated IL-1β (5.6-fold increase in risk) and high expression of iNOS and vimentin (6.3 and 7.9-fold increase in risk) were significant risk factors for the development of comorbidity of PAR and asthma." (PMID 38167134, 2024). "In the univariate analysis, IL-1β (> 10.84 pg/ml), iNOS (> 43.63 pg/ml), and vimentin (> 486.0 pg/ml) were associated with the development of comorbidity of PAR and asthma (p = 0.003, 0.038 and 0.005, respectively)." (PMID 38167134, 2024). "As reported, cough‐variant asthma in vitro models leads to upregulation of N‐cadherin, α‐SMA, and vimentin, and downregulation of E‐cadherin in BEAS‐2B cells." (PMID 36799806, 2023). "Accordingly, asthma mice had suppressed expression of E‐cadherin and increased expression of N‐cadherin, Snail1, and vimentin in our research." (PMID 36799806, 2023). "The direct role of citrullinated vimentin antigen and antibody in mucosal inflammation and asthma needs to be explored." (PMID 35573702, 2022). "Masson staining and immunofluorescence staining of the EMT index (a-SMA, collagen I, N-cadherin, and vimentin) showed a large amount of collagen deposition around the airway of patients with asthma and obvious mesenchymal transformation of epithelial cells." (PMID 35359966, 2022). "Sin also inhibited MMP7, MMP9, and vimentin expression in 16HBE cells and respiratory epithelial cells from mice with asthma." (PMID 34804018, 2021). "In asthma, vimentin-positive basal cells were similar to the HC (P = 0.5150)." (PMID 40475784, 2025). "On the other hand, the vimentin-positive cells in asthma tended to be lower than HC (P = 0.5641)." (PMID 40475784, 2025). "In our OVA-induced asthma model, the mesenchymal marker, vimentin, was increased." (PMID 34804018, 2021). "When comparing the titers of antibody binding, the levels of antibodies to all 3 peptides were significantly increased in BR patients compared with patients with asthma and, in the case of both anti‐vimentin and anti–Cit‐fibrinogen, compared with healthy controls." (PMID 26017630, 2015). "In addition, the titers of anti–REP‐1 and anti‐vimentin were significantly increased in patients with BR compared with both healthy controls and patients with asthma." (PMID 26017630, 2015). "In QFXY-asthma target network, Hsp90α, Mapk3, VIM were hub proteins suggesting that they may be some targets of QFXY pills." (PMID 23919426, 2013). "In asthma, during airway smooth muscle (ASM) remodeling, IL-17, through the ZEB1 pathway, reduces the expression of E-cadherin and increases the expression of vimentin, promoting the thickening of the ASM layer driven by Th17 cells in severe asthma." (PMID 40016707, 2025). "The COPD-CS group also had high vimentin-positive RBM cells, compared to HC and asthma groups (P <0.05 for both)." (PMID 40475784, 2025). "In general, similar to the epithelial basal cells, both vimentin and S100A4 positive cells in the RBM of pathological groups were elevated except in patients with asthma." (PMID 40475784, 2025). "In contrast, the mesenchymal markers N-cadherin percent expression, vimentin, and S100A4 positive cell counts generally increased in all pathological groups except in the patients with asthma." (PMID 40475784, 2025). "Elevated levels of IL-1β, iNOS, and vimentin in the serum were identified as significant indicators of the likelihood of comorbidity of PAR and asthma in children." (PMID 38167134, 2024). "Other studies showed that the gene and/or protein expression of collagen I, fibronectin, versican, elastin, tenascin C, periostin, and vimentin was increased in ASMC and PF in asthma studies, including in vivo, ex vivo, in vitro, and animal model studies." (PMID 35456903, 2022).
asthma (continued). "Taken together, AEO decreased the POSTN and TGF-β expressions in the asthma provoked by allergens and then cadherin switching was promoted by POSTN/TGF-β with the co-expression factors, snail and vimentin." (PMID 35335934, 2022). "This study also demonstrated a trend of high vimentin and S100A4-positive basal and RBM cells in ACO, and an RBM with the elevated degree of fragmentation as represented by the cleft formation in ACO as compared with HC and asthma." (PMID 40475784, 2025). "The vimentin-positive cells appeared to be elevated in the RBM of ACO as compared to HC although the difference was not statistically (P = 0.1610); however, as compared to asthma the increase in vimentin-positive cells was notable (P <0.05)." (PMID 40475784, 2025).
cholangiocarcinoma (15 papers, 2009 to 2025). A carcinoma that arises from the intrahepatic biliary tree (intrahepatic cholangiocarcinoma) or from the junction, or adjacent to the junction, of the right and left hepatic ducts (hilar cholangiocarcinoma). "Similar to our findings, the induction of E-cadherin expression by trichostatin A and valproic acid was sufficient to inhibit cell migration and invasion of cholangiocellular carcinoma cells, even though it also caused an increase in the mesenchymal protein vimentin." (PMID 40806251, 2025). "Histopathological and immunohistochemical examinations indicated a malignant neoplasm that was positive for vimentin and cytokeratin, with these features providing a positive diagnosis for intrahepatic sarcomatoid cholangiocarcinoma." (PMID 36117828, 2022). "Additionally, hepatocytes showed partial positivity, while the mesenchymal marker vimentin showed focal positivity; these findings were distinct from the typical findings of intrahepatic cholangiocarcinoma." (PMID 40755904, 2025). "In relation to the decline of vimentin, we must mention that high expression of vimentin has reportedly shown correlation with poor differentiation in cholangiocarcinoma biopsies and EMT phenotype and, conversely, a decline of vimentin would indicate a reversion of the mesenchymal transition." (PMID 25756965, 2015). "The applicability of GenoCTC to different cell surface biomarkers was also validated in a cholangiocarcinoma patient using anti-EPCAM, anti-vimentin, or anti-tyrosine protein kinase MET (c-MET) antibodies." (PMID 32486306, 2020). "Likewise, a series of experiments performed in this study suggest that Huaier alone or combined with 5-FU could inhibit the invasion and metastasis of cholangiocarcinoma cells and those involved in the down-regulation of N-cadherin, Vimentin, MMP-2 and MMP-9 expression." (PMID 31391034, 2019). "Furthermore, ARK5 appears to regulate the expression of the EMT related markers E-cadherin and vimentin in cholangiocarcinoma cells; in particular, downregulation of ARK5 increased the expression of E-cadherin and decreases the expression of vimentin." (PMID 28832761, 2017). "Moreover, correlation analyses showed that the expression of TBK1 correlated with the expression of E-cadherin (r = −0.3799, P < 0.001) and vimentin (r = 0.3818, P < 0.001), suggesting that TBK1 is highly expressed mainly in mesenchymal phenotype cholangiocarcinoma tissues." (PMID 36928362, 2023). "Here, we enumerated and analyzed CTCs from a cholangiocarcinoma patient using the epithelial marker EPCAM and the non-epithelial markers vimentin and MET." (PMID 32486306, 2020).
synovial sarcoma (15 papers, 2006 to 2025). "The results indicate high expression levels of E-cadherin and cytokeratin 19 in epithelial cells and stronger reactions for vimentin and S100b in spindle cells of biphasic synovial sarcomas." (PMID 41155410, 2025). "Synovial sarcomas are usually positive for vimentin, epithelial membrane antigen (EMA), bcl-2, CD99 (60–90%), and S-100 (30%)." (PMID 26101678, 2015). "Immunohistochemically, most synovial sarcomas are positive for vimentin, cytokeratin and EMA, but have a lower immunoreactivity for S-100 and CD34." (PMID 22741534, 2012). "On the other hand, immunohistochemistry of synovial sarcomas is complex and unique, it includes mesenchymal markers expression such as vimentin and epithelial markers as cytokeratins 19 and 7 and epithelial membrane antigen that are presented in 90% of all cases." (PMID 35086047, 2022). "Immunohistochemically most synovial sarcomas were positive for vimentin, cytokeratins, and EMA and also could show lower immunoreactivity for S-100 and CD34." (PMID 25152824, 2014). "Markers that are commonly expressed on synovial sarcoma cells include epithelial membrane antigen (EMA), BCL-2, and vimentin, while markers such as protein S-100, CD99, CD34, actin, and desmin are mostly negative." (PMID 40130143, 2025). "It has been indicated that vimentin, cytokeratin and EMA positivity, in combination with CD34 negativity, are the most useful protein biomarkers for the diagnosis of monophasic synovial sarcoma." (PMID 24348836, 2014). "The specimens of our patient were uniformly positive for Vimentin, BCL-2 and CD99 (markers which are typical for synovial sarcoma) and showed focal positivity for EMA." (PMID 24715974, 2014). "Immunohistochemical markers, including vimentin, EMA and cytokeratin, are used to aid the pathological diagnosis of synovial sarcoma." (PMID 23833678, 2013). "Synovial sarcomas are negative for desmin, actin, S100 protein, and cytokeratin and positive for vimentin and Bcl-2." (PMID 37927755, 2023). "Synovial sarcoma are also positive for EMA, vimentin, BCL-2, CD99 and calponin." (PMID 16907985, 2006). "In common with other synovial sarcomas, the immunohistochemical staining demonstrated some typical findings of synovial sarcoma: the tumor cells were positive for vimentin and CD99, but negative for CD34, Bcl-2, alpha smooth muscle actin, desmin, and S-100 protein." (PMID 24969223, 2014). "The tumor cells were found to be positive for vimentin, EMA and S100, and negative for CD34, which, in combination with the morphological profile, confirmed the diagnosis of a monophasic synovial sarcoma." (PMID 24348836, 2014). "Immunohistochemistry demonstrated positive staining for epithelial membrane antigen (EMA), vimentin and Bcl-2, but negative staining for CD99, CD34, CD68, S100, cytokeratin, desmin, calretinin, HMBE-1, CK5/6 and smooth muscle actin, confirming a diagnosis of biphasic synovial sarcoma." (PMID 23833678, 2013).
angiosarcoma (14 papers, 2005 to 2024). A malignant tumor arising from the endothelial cells of the blood vessels. "It is also important to note that positive stainings for CD31, CD34, and vimentin are also found in epithelioid angiosarcoma of bone and soft tissue." (PMID 28865487, 2017). "Epithelioid angiosarcomas stain strongly positive for Vimentin and in most cases are immunoreactive for vascular markers CD31, CD34, and VEGFR-3 and Factor VIII." (PMID 26290766, 2015). "Angiosarcomas arise from the endothelial cells of blood vessels and stain for filament proteins vimentin, factor VIII, and CD34." (PMID 17603895, 2007). "Epithelioid angiosarcoma is strongly vimentin and factor VIII positive." (PMID 33520482, 2020). "However, epithelioid angiosarcoma focally shows sinusoid-like spaces and is also positive for vimentin and CD31." (PMID 23819679, 2013). "The cells of angiosarcoma are positively stained for vimentin, the endothelial cell markers such as CD31, CD34, and factor, and negatively for epithelial marker such as cytokeratin and EMA, however, in the epithelioid angiosarcoma, it may be stained as positive." (PMID 16159405, 2005). "Histopathological examination confirmed a diagnosis of angiosarcoma, characterized by pleomorphic tumour cells, a high Ki67 proliferation index and positive immunohistochemical markers, including CD31, D2‐40, Vimentin, and Factor VIII." (PMID 39588325, 2024). "Immunohistochemical markers such as vimentin, CD31, and von Willebrand factor are used to diagnose vascular hamartomas, hemangioma and hemangiosarcoma." (PMID 38895709, 2024). "Immunohistochemical profiling is essential for differentiating PASH from low-grade angiosarcoma, with specific markers such as CD34, vimentin, desmin, actin, and progesterone receptor aiding in the correct diagnosis and preventing misinterpretation." (PMID 39564024, 2024). "Immunohistochemically, the neoplastic cells were immunolabeled for vimentin and CD31, supporting the diagnosis of hemangiosarcoma." (PMID 36669009, 2022). "Other entities, such as angiosarcoma and gastrointestinal stromal tumour, also express CD34 and vimentin epitopes." (PMID 17118185, 2006). "In addition, CD31 immunohistochemistry was identified to be valuable in the differential diagnosis; however, a variety of markers are required for the diagnosis of angiosarcoma, such as CD34, FVIII, vimentin and pan-CK." (PMID 25289092, 2014).